DYRK1A (dual specificity tyrosine phosphorylation regulated kinase 1A)
Diseases named in the same sentence as DYRK1A in open-access papers (continued):
Sharing a sentence is not in itself a finding about the gene and the disease.
liver cancer (2 papers, 2022 to 2025). An epithelial or non-epithelial malignant neoplasm that arises from the liver. "Moreover, high DYRK1A levels were associated with shorter progression-free survival and progression/metastasis-free survival times in liver cancer patients." (PMID 35655269, 2022). "Additionally, alteration of DYRK1A expression was correlated with poor outcomes in patients with liver cancer (n = 365: n = 9 in the altered group and n = 356 in the unaltered group; p < 0.05)." (PMID 35655269, 2022). "Moreover, knockout of NF2, DYRK1A, and SOX9 in another TSPAN8-expressing human liver cancer cell line, SNU878, similarly resulted in a downregulation of TSPAN8." (PMID 40801599, 2025). "Additionally, the level of DYRK1A was increased in primary HCC tissues of patients with metastasis compared with those of patients without metastasis, and DYRK1A overexpression correlated with worse outcomes in liver cancer patients." (PMID 35655269, 2022).
medulloblastoma (2 papers, 2015 to 2016). A malignant, invasive embryonal neoplasm arising from the cerebellum. "In SAG-stimulated human medulloblastoma cells, stable, lentiviral shRNA inhibition of DYRK1A moderately reduced GLI1 and PTCH mRNA expression by 55 and 40 percent, respectively." (PMID 26784250, 2016). "We further verified this finding in human medulloblastoma cells (Daoy), in which the knockdown of DYRK1A led to an increased sensitivity towards the smoothened agonist (SAG)." (PMID 26310823, 2015). "Harmine treatment of murine BCC cells reduced Gli1 expression in a concentration-dependent manner, and like in human medulloblastoma cells, RNAi mediated perturbation of Dyrk1b efficiently inhibited Gli1 protein expression, while depletion of Dyrk1a did not." (PMID 26784250, 2016).
melanoma (2 papers, 2014 to 2021). A malignant, usually aggressive tumor composed of atypical, neoplastic melanocytes. "MITF drives most of the melanocytic markers, and interestingly, DYRK1A mRNA is downregulated in melanoma cell lines." (PMID 24901999, 2014). "DYRK1A was found to be downregulated in melanoma, and overexpressed in the activation of T-cells." (PMID 24901999, 2014).
oral squamous cell carcinoma (2 papers, 2022). "Interestingly, DYRK1A was recently reported to play a role in cancer stemness in oral squamous cell carcinoma." (PMID 35454940, 2022).
pancreatic ductal adenocarcinoma (2 papers, 2021 to 2022). An infiltrating adenocarcinoma that arises from the epithelial cells of the pancreas. "USP22 was also been reported to accelerate the development of cancer cells by targeting the DYRK1A in pancreatic ductal adenocarcinoma." (PMID 34753387, 2021). "In pancreatic ductal adenocarcinoma (PDAC) cells, USP22 stimulated cell growth via targeting dual-specificity tyrosine regulated kinase 1A (DYRK1A)." (PMID 35692754, 2022).
psoriasis (2 papers, 2023 to 2025). An autoimmune condition characterized by red, well-delineated plaques with silvery scales that are usually on the extensor surfaces and scalp. "Overexpression of miR-215-5p inhibited the proliferation of human keratinocytes (HaCaTs) cell and diminished psoriasis-like inflammation through DYRK1A-mediated regulation of the EGFR signaling pathway." (PMID 40861221, 2025). "In psoriasis, miR-215 is reported to be downregulated in the skin lesion tissues in humans and mouse models, with the functional role validated in a keratinocyte-specific study, wherein miR-215 is shown to target DYRK1A and dysregulate keratinocyte proliferation via EGFR signaling." (PMID 37700769, 2023). "Dual-tyrosine specificity phosphorylation-regulated kinase 1A (DYRK1A) is a key stabilizer of the epidermal growth factor receptor (EGFR) and plays a crucial role in cytokeratinization, hyperproliferation, aberrant differentiation, and inflammatory infiltration during the development of psoriasis." (PMID 40861221, 2025).
rheumatoid arthritis (2 papers, 2024 to 2025). A chronic, systemic autoimmune disorder characterized by inflammation in the synovial membranes and articular surfaces. "It has been demonstrated that DYRK1A overexpression results in increased ERK signaling output in brain cells and synovial tissues of rheumatoid arthritis patients." (PMID 40148558, 2025). "Additionally, DYRK1A has been found to be a promoter of fibroblast-like synoviocytes (FLS), which play a role in cartilage/bone destruction in rheumatoid arthritis (RA) via activation of the ERK/MAPK pathway." (PMID 39308945, 2024).
abdominal obesity metabolic syndrome-3 (1 paper, 2020). "Although both kinases share substrates, the distinct clinical outcome of inactivating mutations indicates they are not functionally redundant, i.e., a disorder within the autism spectrum for DYRK1A and a metabolic syndrome for DYRK1B (abdominal obesity metabolic syndrome-3, OMIM#615812;)." (PMID 32751160, 2020).
acute megakaryoblastic leukemia (1 paper, 2023). Acute megakaryoblastic leukemia (AMKL) is a form of acute myeloid leukemia (AML) that occurs predominantly in childhood and particularly in children with Down syndrome (DS-AMKL). "On the other hand, the overexpression of DYRK1A in the DS-specific B-cell acute lymphoblastic leukemia (B-ALL) and acute megakaryoblastic leukemia (AMKL) has been shown to target distinct cellular pathways." (PMID 37900285, 2023).
AIDS (1 paper, 2011). A syndrome resulting from the acquired deficiency of cellular immunity caused by the human immunodeficiency virus (HIV). "In addition to the SNP in DYRK1A we also found associations for rs17519417 in SPOCK3 with time to progression to AIDS." (PMID 21364930, 2011).
asthma (1 paper, 2023). "This could point to a possible functional link between GLCCI1 and DYRK1A in asthma, and further characterization of the role of DYRK1A in the GLCCI1 function could potentially lead to new avenues in asthma research." (PMID 37900285, 2023).
autosomal recessive primary microcephaly (1 paper, 2016). Autosomal recessive primary microcephaly (MCPH) is a rare genetically heterogeneous disorder of neurogenic brain development characterized by reduced head circumference at birth with no gross anomalies of brain architecture and variable degrees of intellectual impairment. "To date, 16 loci and genes have been associated with autosomal recessive primary microcephaly (MCPH), and two genes, KIF11 and DYRK1A, have been linked to autosomal dominant primary microcephaly." (PMID 27008544, 2016).
B-cell acute lymphoblastic leukemia (1 paper, 2024). A neoplasm of lymphoblasts committed to the B-cell lineage, typically composed of small to medium-sized blast cells. "Dual specificity tyrosine phosphorylation regulated kinase 1 A (DYRK1A) promoted the development of B-cell acute lymphoblastic leukemia through the phosphorylation of FOXO1." (PMID 38795132, 2024).
behavioural disorders (1 paper, 2021). "In specific, we found that miR‐211‐5p deficits mediated CUMS‐induced neuronal apoptosis and behavioural disorders via activation of the Dyrk1A/ASK1/JNK/P38 pathway within the CA1 area of CUMS‐exposed rats." (PMID 34121317, 2021).
blood pressure (1 paper, 2022). "As niraparib inhibits DYRK1A, increased levels of these neurotransmitters would be seen,which in turn have inotropic effects on the heart, causing high blood pressure." (PMID 35401230, 2022).
Brain atrophy (1 paper, 2020). Partial or complete wasting (loss) of brain tissue that was once present. "Here, we present a patient with DYRK1A haploinsufficiency syndrome, including facial dysmorphism, delayed motor development, cardiovascular system defects, and brain atrophy." (PMID 32555303, 2020).
breast tumors (1 paper, 2024). "Thus, DYRK1A role in breast tumor formation and progression may be context dependent and/or subtype specific and clearly needs further investigation." (PMID 38839871, 2024).
Chorioretinal atrophy (1 paper, 2025). Atrophy (wasting) of the choroid and retinal layers of the fundus. "However, KIF11-associated disease is also associated with chorioretinal atrophy—absent in our patients with DYRK1A-associated retinopathy—highlighting this as a potentially useful clinical marker to distinguish between the two." (PMID 40405340, 2025).
congenital cataracts (1 paper, 2023). "Patient #3 had a deletion in chromosome 21, including the RUNX1, DYRK1A, and KCNJ6 genes, classified as likely pathogenic as variants in DYRK1A have been associated with bilateral congenital cataracts." (PMID 36980880, 2023).
deficiencies (1 paper, 2024). "The skeletal abnormalities found in Dyrk1a haploinsufficient mice may portend similar skeletal deficiencies in humans with DYRK1A haploinsufficiency." (PMID 39308945, 2024).
diffuse large B-cell lymphoma (1 paper, 2023). "While a majority of the solid tumor TCGA datasets display a DYRK1A gene copy number loss, several cancers including testicular germ cell cancer, diffuse large B-cell lymphoma and uveal melanoma display high rates of an increased DYRK1A gene dosage." (PMID 37900285, 2023).
dopaminergic neuroblastoma (1 paper, 2021). A neuroblastoma associated with increased dopamine excretion. "We next examined whether DYRK1A binds to two PPM family proteins (PPM1A and PPM1B) in other mammalian cells, such as dopaminergic neuroblastoma SH-SY5Y cells." (PMID 33380426, 2021).
fatty liver (1 paper, 2025). "In this study, through network pharmacology and molecular docking, we identified potential targets for Catechin gallate in the treatment of fatty liver disease, which include ABCB1, DYRK1A, PGD, and FUT4." (PMID 40699724, 2025). "Furthermore, based on network pharmacology predictions, molecular docking studies suggested that the primary targets of Catechin gallate in alleviating fatty liver might include ABCB1, DYRK1A, PGD, and FUT4." (PMID 40699724, 2025).
heart defects (1 paper, 2024). "Using systematic genetic mapping, we determined that three copies of the dual-specificity tyrosine phosphorylation-regulated kinase 1A (Dyrk1a) gene, encoding a serine/threonine protein kinase, are associated with congenital heart disease pathology." (PMID 38266108, 2024). "Increased dosage of DYRK1A results in impairment of mitochondrial function and congenital heart disease pathology in mice with DS, suggesting that DYRK1A may be a useful therapeutic target for treating this common human condition." (PMID 38266108, 2024). "The work presented here shows that mitochondrial dysfunction and reduced cell proliferation correlate with congenital heart defects and that all three of these depend on a third copy of Dyrk1a, however the results do not prove that these cellular changes cause septation defects." (PMID 38266108, 2024).
heart injury (1 paper, 2022). Injury to the heart. "Our study provides evidence that DYRK1A is a promising target for the promotion of cardiomyocyte cell cycle reentry and cardiac repair after heart injury, especially MI." (PMID 35810562, 2022).
HIV-1 infection (1 paper, 2011). The type species of lentivirus and the etiologic agent of acquired immunodeficiency syndrome (AIDS). "The finding that the SNP rs12483205 in DYRK1A was associated with in vivo endpoints could indicate a role for HIV-1 infection of macrophages in disease progression." (PMID 21364930, 2011).
Infertility (1 paper, 2021). "In order to characterize the mechanism by which DYRK1A alone might cause infertility in men with DS, we studied the fertility of a transgenic mouse model overexpressing Dyrk1A (hereafter referred to as the Tg mouse)." (PMID 34828406, 2021). "To better ascertain DYRK1A’s role in infertility in DS, we investigated the effect of DYRK1A overexpression in a transgenic mouse model." (PMID 34828406, 2021). "Thus, DYRK1A may well be involved in the pathogenesis of infertility in DS." (PMID 34828406, 2021).
ischemia (1 paper, 2025). A hypoperfusion of the BLOOD through an organ or tissue caused by a PATHOLOGIC CONSTRICTION or obstruction of its BLOOD VESSELS, or an absence of BLOOD CIRCULATION. "Previous studies have shown that pharmacological inhibition of DYRK1A using harmine induces cardiomyocyte cell cycle re-entry after ischemia/reperfusion (I/R) MI." (PMID 40901489, 2025).
laminopathy (1 paper, 2023). A rare genetic disorder caused by mutations in genes encoding proteins of the nuclear lamina. "This opens up a theoretical possibility of early therapeutic interventions quenching the action of DYRK1A, in order to restore the levels of Lamin B1, and stop further development of laminopathy-associated phenotypes." (PMID 37451904, 2023). "Treatment of T-CRO1 organoids with DYRK1A inhibitors for 40 days significantly reduced the DSB and p21 values, and restored the Lamin B1 levels, demonstrating that this senescence and laminopathy-associated effect of DYRK1A can be, in principle, chemically counter-acted." (PMID 37451904, 2023). "We next questioned if a link could be established between laminopathy in DS foetal tissues, and the laminopathy and DNA damage driven by DYRK1A, seen in hiPSC models." (PMID 37451904, 2023).
liver disease (1 paper, 2023). "We previously demonstrated significant decreased concentrations of plasma alanine aminotransferase, a biomarker for diagnosis liver disease and reflecting liver damage, in plasma of mice overexpressing Dyrk1A, showing protective effect of increased Dyrk1A on liver function." (PMID 37415307, 2023).
lung adenocarcinoma (1 paper, 2024). A carcinoma that arises from the lung and is characterized by the presence of malignant glandular epithelial cells. "To further expand the scope and relevance of our findings, we also assessed DYRK1A inhibition in other cancer models, including lung adenocarcinoma (A459) and the immortalized HeLa cell lines." (PMID 38839871, 2024).
metastatic tumors (1 paper, 2024). "It will be interesting in future studies, to address whether DYRK1A inhibition could also prove useful for treating the progression of metastatic tumors, by assessing the pharmacological inhibition of DYRK1A in already established metastatic tumors." (PMID 38839871, 2024).
microphthalmia (1 paper, 2025). Congenital or developmental anomaly in which the eyeballs are abnormally small. "Dyrk1a± mice demonstrate microphthalmia, thinner retinas, reduced retinal ganglion cell numbers, abnormal retinal function on ERG, and defects in developmental retinal vascularization, with Dyrk1a proposed to play a key role in regulating endothelial cell proliferation and angiogenesis." (PMID 40405340, 2025).
mucinous colorectal adenocarcinoma (1 paper, 2022). "Intriguingly, high expression of DYRK1A was associated with mucinous colorectal adenocarcinoma." (PMID 35454940, 2022).
Neurofibrillary tangles (1 paper, 2022). Pathological protein aggregates formed by hyperphosphorylation of a microtubule-associated protein known as tau, causing it to aggregate in an insoluble form. "Based on the present study outcome, we propose four antagonists, viz., ZINC3843365, ZINC2123081, ZINC5220992, and ZINC68569602 as potential inhibitors against DYRK1A and to reduce the amyloid-β and neurofibrillary tangle burden." (PMID 36741918, 2022).
oropharyngeal squamous cell carcinoma (1 paper, 2022). "It has been shown that DYRK1A is required for the maintenance of cancer stemness, contributing to tumorigenic potential in oral/oropharyngeal squamous cell carcinoma." (PMID 36362284, 2022).
otitis media (1 paper, 2025). Inflammation of the anatomical structures of the middle ear, which is most often caused by an infectious process. "For instance, how do other genes within the implicated region interact with DYRK1A to influence the likelihood of developing otitis media?" (PMID 39840732, 2025). "Reducing the amount of DYRK1A expressed in the mouse models restored middle ear health, convincingly linking DYRK1A to the development of otitis media." (PMID 39840732, 2025).
Senile plaques (1 paper, 2021). Senile plaques are extracellular deposits of amyloid in the gray matter of the brain. "Therefore, inhibition of DYRK1A by PPM1B may or may not also modulate these multiple factors in concert, affecting the formation of Aβ-containing senile plaques or α-synuclein-containing Lewy bodies and the progression of AD and PD." (PMID 33380426, 2021).
skin tumors (1 paper, 2016). "Although we did not perturb Dyrk1a dosage in our in vivo model, it is worth being cautious of its role in tumorigenesis in skin tumors." (PMID 26752700, 2016).
Splenomegaly (1 paper, 2023). Abnormal increased size of the spleen. "Moreover, we only found a decrease platelet number by 25% in mice overexpressing Dyrk1A, this decrease being not due to splenomegaly, no accelerated platelet clearance with an unchanged platelet volume." (PMID 37415307, 2023).
Stroke (1 paper, 2018). Sudden impairment of blood flow to a part of the brain due to occlusion or rupture of an artery to the brain. "Our association results in combination with the eQTL data further point to a potential role of DYRK1A in stroke." (PMID 30383316, 2018).
tendinopathy (1 paper, 2024). "Biosplice Therapeutics is currently developing SM04755, a CLK2 and dual-specificity tyrosine phosphorylation-regulated kinase 1A (DYRK1A) inhibitor, as an experimental treatment for tendinopathy." (PMID 39065798, 2024).
Thrombocytopenia (1 paper, 2023). A reduction in the number of circulating thrombocytes. "Thus, the thrombocytopenia is far from being constant as expected from an overexpression of DyrK1A." (PMID 37415307, 2023).
Tremor (1 paper, 2019). An unintentional, oscillating to-and-fro muscle movement about a joint axis. "In various experiments targeting DYRK1A, EGCG or green tea extracts have been compared to harmine, a more potent inhibitor of DYRK1A but which is also inducing tremors." (PMID 30850713, 2019).
trisomy (1 paper, 2023). A chromosomal abnormality consisting of the presence of one chromosome in addition to the normal diploid number. "Thus, DYRK1A has long been considered a key player that potentially underlies the characteristic presentations of Trisomy 21, with the third copy of the DYRK1A gene implicated in disease aetiology." (PMID 37607329, 2023).